MEN1 (menin 1)
Diseases named in the same sentence as MEN1 in open-access papers (continued):
Sharing a sentence is not in itself a finding about the gene and the disease.
carcinoids (45 papers, 2008 to 2025). "Typical and atypical carcinoids often harbor mutations in the MEN1 gene and exhibit low proliferation rates, which correlate with their generally indolent clinical behavior." (PMID 40586102, 2025). "These genetic alterations are known to influence gene expression and can act as confounding factors, as demonstrated in carcinoid tumors (e.g., MEN1 mutations) and LCNEC." (PMID 40586102, 2025). "Carcinoid tumors present with lower mutational burdens, often harboring somatic mutations in chromatin remodeling genes, such as MEN1 and ATRX." (PMID 40586102, 2025). "Among the most frequent mutations are those affecting the menin gene (MEN1), similar to the typical carcinoid of the thymus." (PMID 40843719, 2025). "A small subset of carcinoids can be seen in patients with multiple endocrine neoplasia 1 (MEN1) syndrome (OMIM#131100), while somatic MEN1 gene mutations are commonly observed in carcinoids." (PMID 37509621, 2023). "In fact, although mutation rates of EIF1AX and ARID1A are in line with those of typical carcinoids, a higher prevalence of MEN1 mutations is observed in atypical carcinoids as compared with typical carcinoids, reaching 25%." (PMID 33641055, 2021). "A family history of carcinoid tumors and carrying the Multiple Endocrine Neoplasia type 1 (MEN1) gene are risk factors for carcinoid development." (PMID 32923302, 2020). "Of note, MEN1 mutations were significantly associated with the atypical carcinoid histopathological subtype (Fisher’s exact test p-value = 0.0096), as well as MOFA LNEN LF2." (PMID 31431620, 2019). "MEN1-associated carcinoid tumors include thymic, bronchial, and gastric enterochromaffin-like cell NETs." (PMID 31263451, 2019). "On the other hand, mutations of the multiple endocrine neoplasia type 1 (MEN1) gene are restricted to carcinoid tumors." (PMID 23119202, 2012). "This included HRAS (11p15) amplification on chromothriptic chromosome 11, KRAS (12q12) and ERBB3 (12q13) amplification on chromosome 12, as well as deletions of key carcinoid-associated tumor suppressor genes MEN1 (11q13) and ARID1A (1p36) on chromosomes 11 and 1, respectively." (PMID 39185963, 2025). "MEN1 in carcinoids (9–11%), is normally associated with a loss of heterozygosity of chr.11." (PMID 35626118, 2022). "The third group presented with a carcinoid-like morphology and MEN1 gene mutation." (PMID 34307132, 2021). "This allows localization of small duodenal lesions/accompanying lymph node metastases and assessment for more distant metastases, as well as assessment for other MEN1 accompanying NETs (carcinoids [lung, thymic, gastric], NF-pNET, meningiomas)." (PMID 41463062, 2025). "Other manifestations of MEN1 include adrenal adenomas, carcinoid tumors, or dermatological manifestations." (PMID 40144450, 2025). "In another carcinoid-study, carcinoids showed MEN1 gene alterations, resulting in failures of chromatin remodeling, while LCNEC were characterized by mutations in DNA repair genes (loss of orthopedia homeobox) and upregulation of the RET gene." (PMID 34307132, 2021).
carcinoids (continued). "Other endocrine tumors in MEN1 include foregut carcinoid tumors, adrenocortical tumors, and rarely pheochromocytoma." (PMID 31263451, 2019). "LOH in MEN1 was significantly more frequent in carcinoids than in carcinomas (TCs, 15.1%; ACs, 22.9%; LCNECs, 3.7%; SCLCs, 0%; p = 0.011)." (PMID 27873319, 2017). "Atypical and typical carcinoid tumors are characterized by a frequent deletion of 11 q material including the MEN1 gene locus." (PMID 22269186, 2012). "Michele Simbolo and colleagues’ work on carcinoids reveals differential gene expression, with atypical carcinoids (AC) showing increases in genes such as TERT and SDHA, and typical carcinoids (TC) showing a loss in MEN1." (PMID 38539512, 2024). "Indeed, mutations in genes involved in chromatin remodeling are detected with a high frequency (~40%) in carcinoids, the most frequent being MEN1 (11–22%), genes of the SWI/SNF complex mostly affecting ARID1A (6–7% of cases) and KMT2C/MLL3 (8%)." (PMID 38893145, 2024). "Deletions in the MEN1 locus at 11q are common in both typical and atypical carcinoids." (PMID 38001701, 2023). "Up to 33% of MEN1 patients may develop breast carcinoma, and up to 25% may develop carcinoids (thymic, bronchial, Type II gastric enterochromaffin-like carcinoid)." (PMID 37239385, 2023). "A small subset of LCNEC has alterations of MEN-1 with histologic features of carcinoid." (PMID 34178652, 2021). "Patients with MEN1 may develop parathyroid, pituitary, adrenocortical, gastroenteropancreatic neuroendocrine, and carcinoid tumors as well as lipomas, collagenomas, meningioma, and facial angiofibromas." (PMID 30990521, 2019). "There were fewer CNAs in carcinoids than in carcinomas; however ACs showed a hybrid pattern, whereby gains of TERT, SDHA, RICTOR, PIK3CA, MYCL and SRC were found at rates similar to those in carcinomas, whereas the MEN1 loss rate mirrored that of TCs." (PMID 27873319, 2017). "This suggests that the co-occurrence of carcinoids with one of the main MEN1-related tumor may represent a true MEN1." (PMID 29036195, 2017). "In addition to these tumors, adrenal cortical tumors, carcinoid, facial angiofibromas, collagenomas, and lipomatous tumors have been described in patients with MEN1." (PMID 23933118, 2014). "It should be mentioned that carcinoid is not infrequently associated with MEN1 and loss of 11q, sometimes independently of the MEN1 gene (11q13), suggesting loss of MEN1 or another tumour suppressor gene is responsible for the condition." (PMID 18761734, 2008). "In addition to these, other MEN1-associated endocrine (i.e., adrenocortical tumors, and carcinoids) and non-endocrine (i.e., facial angiofibromas, collagenomas, lipomas, meningiomas) tumors have been described in MEN1 patients." (PMID 33066578, 2020). "In addition, some MEN1 patients may also develop adrenocortical tumors, lipomas, carcinoid tumors, facial angiofibromas and collagenomas." (PMID 23933118, 2014).
carcinoids (continued). "Of note, atypical carcinoids usually carry more alterations in the MEN1 (22% vs. 6%) and PIK3CA genes (39% vs. 13%) compared to typical carcinoids." (PMID 38893145, 2024). "Carcinoid tumors, such as thymic, bronchial, and type II gastric enterochromaffin-like (ECL) carcinoids, occur in 3–10% of individuals with MEN1." (PMID 39336996, 2024). "In a cohort of 57 patients with MEN1 and ZES, ECL proliferative changes were universally present, whereas advanced changes were noted in 53% and carcinoids were diagnosed in 23%." (PMID 31263451, 2019). "Adrenal tumors, which are primarily nonfunctional, and thyroid tumors can occur in <50%, and MEN1 patients have an increased incidence of carcinoids (stomach, lung, thymus)." (PMID 41463062, 2025). "The correlation between MEN1 and PYGM is worth noting, because the losses of heterozygosity regarding the 11q13 chromosome are often observed not only in MEN1 but also in the case of sporadic carcinoid tumors of the lung and invasive breast cancers." (PMID 33924466, 2021). "As in MEN1, other types of tumors may develop in patients with MEN4, including carcinoid tumors and meningioma." (PMID 30990521, 2019). "Even among sporadic carcinoids in patients without other features suggestive of MEN1 syndrome, it is felt that the MEN1 gene may act as a tumor suppressor gene and sporadic carcinoid tumors have demonstrated genetic abnormalities in the MEN1 gene." (PMID 41216113, 2025). "Overall, based on histopathology, OTP expression, and/or presence of genomic alterations that, although not entirely specific, are highly characteristic of carcinoid tumors (MEN1 and EIF1AX), 55% of aSCLC exhibited features of a histogenetic relationship with pulmonary carcinoids." (PMID 39185963, 2025). "Adding to the intrinsic burden of MEN1, a different combination of endocrine and non-endocrine tumors may develop, i.e. carcinoids (thymic, bronchial), adrenocortical tumors, facial angiofibromas, lipomas, and collagenomas." (PMID 33312161, 2020).
breast cancer (43 papers, 2010 to 2025). A primary or metastatic malignant neoplasm involving the breast. "Nonetheless, additional research is needed to explore potential associations between MEN-1 and breast cancer." (PMID 37933321, 2023). "MEN1 deficiency is widely associated with an increased risk of developing breast cancer in female patients with MEN1 syndrome." (PMID 37437063, 2023). "Disruption in hormonal balance due to MEN1 mutations or its altered expression can potentially contribute to breast cancer development." (PMID 37437063, 2023). "Increased risk and an early-onset of breast cancer have been reported in MEN1-mutated women than in the general population, and therefore, breast cancer surveillance should be started 10 years earlier in the former than in the latter women." (PMID 37484956, 2023). "Previous researches indicated the enigmatic role of MEN1 in breast cancer, where its positive association is evident with ERα and ESR." (PMID 37437063, 2023). "The C terminal of MEN1 protein has nucleus localizing sequences that are critical for its nuclear import; however there are very limited instances where MEN1 mutations in cases of sporadic breast cancer are reported." (PMID 37437063, 2023). "Given the increased risk, a Dutch study suggested starting breast cancer screening from the age of 40 in MEN1 women." (PMID 37484956, 2023). "Earlier studies on women with sporadic breast cancer and those with the MEN1 syndrome have underlined the contradicting role of MEN1 in the disease." (PMID 37437063, 2023). "As suggested by Brennan, more extensive LOH studies are required to determine the extent of chromosome 11q loss in breast tumors from MEN1 patients compared with matched, sporadic breast cancer controls." (PMID 36325452, 2022). "Elevated expression of RNF126 has been reported as a prognostic biomarker in breast cancer, a cancer type associated with MEN1 gene mutations." (PMID 35941657, 2022). "In a later study looking at the molecular landscape in 560 breast cancers, somatic MEN1 mutations were extraordinarily rare." (PMID 36325452, 2022). "In summary, it has recently been suggested that the risk of breast carcinoma is increased in women with MEN1, but further studies are required to prove causality with more certainty." (PMID 36325452, 2022). "Most recently, it has been proposed that the risk of breast carcinoma is heightened in females with MEN1." (PMID 36325452, 2022). "As confirmed in one of our study patients, pathogenic variants in the MEN1 gene are associated with a higher incidence of breast cancer and NET." (PMID 31592449, 2019). "Several other studies have also described cases of patients with MEN1 and a family history of breast cancer, however, in these studies, the breast cancer was caused by mutations of the BRCA1/2 gene not the MEN1 gene." (PMID 24959251, 2014). "In summary, the current study presented the rare case of a patient with MEN1 associated with breast cancer, in which a germline mutation of the MEN1 gene was detected." (PMID 24959251, 2014). "The present study reports the case a patient with an unusual combination of MEN1-associated tumors and breast cancer." (PMID 24959251, 2014). "The present study reports a rare case of MEN1 associated with breast cancer with the MEN1 gene mutation." (PMID 24959251, 2014). "However, the contradictory role of MEN1 in sporadic breast cancer cases is observed where it is linked to tumorigenesis through coactivation of ERα." (PMID 37437063, 2023). "Our results indicate upregulated expression of MEN1 in sporadic breast cancer patients and it could be critically associated with development and advancement of the disease." (PMID 37437063, 2023). "However, as these neoplasms are common also in the general population and since the role of MEN1 gene in the thyroid and breast cancers is uncertain, the association of thyroid and breast tumors and MEN1 is considered incidental." (PMID 31249555, 2019).
breast cancer (continued). "Therefore, the risk of breast cancer could theoretically be heightened inwomen with MEN1 who concomitantly have hyperprolactinemia/prolactinoma." (PMID 36325452, 2022). "MEN1 has been reported to act as an oncogenic factor in various solid tumors, such as hepatocellular carcinoma, breast cancer, and PCa." (PMID 40860343, 2025). "Single mutations were identified in MEN1 for gastric cancer, MSH6 for colorectal cancer, CDKN2A for pancreatic cancer, and EPCAM/TSC2/GALNT12 for breast cancer." (PMID 38201513, 2023). "The findings of our study provide better insight in understanding the clinical significance of MEN1 gene in the breast cancer cases." (PMID 37437063, 2023). "Most of the cases had unmethylated (53.52%) MEN1 promoter region, which can be a key factor responsible for dysregulated expression of MEN1 in breast cancer cases." (PMID 37437063, 2023). "In advanced stages III and IV of breast cancer, a strong correlation (p = 0.034) with unmethylated promoter region was observed, with 80.26% (61/76) cases having unmethylated MEN1 promoter region." (PMID 37437063, 2023). "Our findings can be pioneer for further research to determine if MEN1 plays a tumor suppressive or oncogenic role in breast cancer." (PMID 37437063, 2023). "The findings of our study reveal the upregulated expression of MEN1 mRNA in nearly 63% of breast cancer cases." (PMID 37437063, 2023). "Our study targets to find the role of MEN1 gene aberration and its clinical significance in breast cancer." (PMID 37437063, 2023). "In conclusion, our study demonstrates the higher expression of MEN1 in sporadic breast cancer patients." (PMID 37437063, 2023). "In the recently published literature, probable role of MEN1 in ESR expression is reported in ER+ breast cancer cell." (PMID 37437063, 2023). "Thereby our study targets to untangle MEN1 expression at mRNA and protein level and also evaluate its epigenetic and polymorphic alterations in sporadic breast cancer patients." (PMID 37437063, 2023). "The overexpression of the MEN1 gene in Indian breast cancer patients is reported for the first time in our study and it exhibits substantial correlation with the ER+ status of the patients." (PMID 37437063, 2023). "The previously published literature signifies the distinctive functions of MEN1 in breast cancer patients and also provides scope to evaluate its anomalous expression and connection with clinical parameters." (PMID 37437063, 2023). "Scaffold protein menin, encoded by multiple endocrine neoplasia 1 gene (MEN1) and known to be involved in histone modification and epigenetic gene regulation, has been shown to physically bind DOT1L in leukaemia and breast cancer cells." (PMID 36333801, 2022). "In 2014, a study from the Netherlands reported the incidence of breast cancer from the Dutch longitudinal MEN1 database." (PMID 36325452, 2022). "Although CNS tumors, melanoma, and, most recently, breast cancer have been reported as MEN1 clinical manifestations, the published evidence to date is not yet of sufficient high quality to include these tumors in the MEN1 clinical spectrum." (PMID 36325452, 2022). "If breast cancer is indeed part of the MEN1 tumor spectrum, it appears to be one with a relatively low clinical penetrance and without a clearly heightened risk of death from metastatic disease." (PMID 36325452, 2022). "In total, amongst all the databases, there were 44 cases of breast cancer in 865 female MEN1 patients (5.1%) at an average age of diagnosis of 50 years." (PMID 36325452, 2022). "Although CNS tumors, melanoma, and, most recently, breast cancer have been reported as MEN1 clinical manifestations, the published evidence to date is not yet sufficient to establish causality." (PMID 36325452, 2022). "To further investigate how this aberrant expression contributes to tumorigenesis, we performed an RNA-seq analysis of MEN1 shRNA knockdown in two ERα-positive breast cancer cell lines T47D and MCF-7, respectively." (PMID 32971831, 2020).